KITLG (KIT ligand)
Diseases named in the same sentence as KITLG in open-access papers (continued):
Sharing a sentence is not in itself a finding about the gene and the disease.
prostate carcinoma (10 papers, 2012 to 2025). A carcinoma that arises from epithelial cells of the prostate gland. "Platelet-derived stem cell factor (SCF, Kit Ligand, Steel Factor) correlated with prostate cancer severity." (PMID 35515124, 2022). "Stem cell factor (SCF, Kit Ligand) is increased in advanced prostate cancer patient platelet releasates." (PMID 35515124, 2022). "Abnormal expression of KITLG and its receptor KIT has been reported in multiple epithelial-derived cancers, including breast, lung, and prostate cancers." (PMID 40781225, 2025). "To determine how CD117 expression and activation by its ligand stem cell factor (SCF, kit ligand, steel factor) alter prostate cancer aggressiveness, we used C4-2 and PC3-mm human prostate cancer cells, which contain a CD117+ subpopulation." (PMID 33446896, 2021). "Recently, KITLG/c-Kit was found to be involved in CSC maintenance in different cancer types, including prostate cancer." (PMID 25978029, 2016). "Meanwhile, we also observed a significant increase in HSC factors/markers (KITLG, CXCR4 and FGF1) in Tie-2High PC-3 cells when compared to the Tie-2Low population, further suggesting that Tie-2High prostate cancer cells are similar to HSCs." (PMID 25978029, 2016).
viral infection (10 papers, 2013 to 2025). "Furthermore, the genes EFNA1 and KITLG, which are associated with viral infection, were found in both enriched pathways, suggesting their potential as therapeutic or preventive targets for PDCoV infection." (PMID 38675921, 2024). "The differential genes such as KITLG, FOXP3, miR-451, IL-2, IL-10, IL-6, and TNF-α are mainly involved in viral infection and the immune-inflammatory responses." (PMID 34867371, 2021). "These pathways allowed the identification of PLA2G1B (phospholipase A2 group IB) and KITLG (KIT ligand) DEGs, and both were considered as strongly related to viral infection." (PMID 34696484, 2021).
allergic disease (9 papers, 2009 to 2025). An immune response that occurs following re-exposure to an innocuous antigen, and that requires the presence of existing antibodies against that antigen. "In HCC, KITLG has been found to be an independent prognostic factor, and it can bind to c-kit receptor expressed by various immune cell types, leading to pathological process of allergy." (PMID 33790969, 2021).
germ cell tumor (8 papers, 2013 to 2024). A benign or malignant, gonadal or extragonadal neoplasm that originates from germ cells. "Concurrently, KITLG is prone to a mutation in germ cell tumors, entailing a presumed connection to tumorigenesis." (PMID 38213737, 2024). "Apart from these SNPs, other genetic alterations of the KIT/KITLG pathway have been linked to an increased susceptibility to testicular germ cell tumors." (PMID 28036409, 2016). "It has been reported that polymorphisms in KITLG are likely associated with germ cell tumors." (PMID 33568072, 2021). "Notably, two independent GWAS found that allele variations in KITLG (the unique ligand for the receptor tyrosine kinase KIT) were the strongest genetic risk factors for testicular germ cell tumors." (PMID 28036409, 2016). "The KITLG locus was initially identified as a cancer susceptibility locus for human testicular germ cell tumors in two independent GWASs, although the specific mutation and mechanism of action remains unknown." (PMID 23555311, 2013). "Gonadal biopsy and immunohistochemical biomarkers (OCT3/4 (POU5F1), TSPY, SOX9, FOXL2 and KITLG (SCF)) are important to characterize situations in which GCC development is possible (germ cells tumors)." (PMID 31721911, 2019). "Recent advances have implicated the KITLG/SPRY4/BAK1 and TGFβ/BMP-signaling (BMPR1B) pathways in germ cell tumor development, which include the control of differentiation, cell proliferation and apoptosis." (PMID 23599692, 2013).
lung adenocarcinoma (8 papers, 2014 to 2024). A carcinoma that arises from the lung and is characterized by the presence of malignant glandular epithelial cells. "More recently, we have reported that nicotine can enhance the self-renewal of a subset of lung adenocarcinoma cells enriched in stem-like cell populations, through the induction of c-Kit ligand/Stem Cell Factor (SCF)." (PMID 30322398, 2018).
non-small cell lung carcinoma (8 papers, 2014 to 2025). A group of at least three distinct histological types of lung cancer, including non-small cell squamous cell carcinoma, adenocarcinoma, and large cell carcinoma. "The c-KIT/KITLG axis plays an important role in the self-renewal and proliferation of cancer stem cells in non-small-cell lung cancer." (PMID 25213795, 2014).
squamous cell carcinoma (7 papers, 2014 to 2023). A carcinoma arising from squamous epithelial cells. "In summary, detecting the copy number variation of the KITLG locus in black giant schnauzers is a promising new tool to predict the individual risk of developing squamous cell carcinoma of the digit." (PMID 36851451, 2023). "An example of natural and artificial selection acting in opposite directions might be the widespread duplication upstream of the KITLG gene, which is linked to the increased risk for squamous cell carcinoma in black standard poodles." (PMID 29258433, 2017). "We previously showed that the copy number (CN) variation at the KITLG gene significantly correlates with the likelihood of developing squamous cell carcinoma at the toe in black giant schnauzers." (PMID 37370500, 2023). "Thus, including CNV analysis of the KITLG locus in breeding decisions is complex, and the prevention of squamous cell carcinoma of the digit in giant schnauzers remains challenging for breeders." (PMID 36851451, 2023). "The aim of the study was to evaluate a hypothetical correlation between histological features of invasiveness in canine digital squamous cell carcinoma, based on two different adapted histological grading systems (IFGS and TCBGS), and copy number values of KITLG." (PMID 36851392, 2023).
systemic mastocytosis (7 papers, 2016 to 2025). Systemic mastocytosis (SM) comprises a heterogeneous group of rare acquired and chronic hematological malignancies that are related to an abnormal proliferation of mast cells in tissue, including bone marrow, with or without skin involvement. "Systemic mastocytosis (SM) is an uncommon illness characterized by the multiorgan accumulation of clonal MCs that differentiate less dependently on the natural KIT ligand (SCF) because of somatic mutations in c-KIT (D816V mutation presents in over 90% of adult patients)." (PMID 40175843, 2025).
testicular cancer (7 papers, 2012 to 2023). A primary or metastatic malignant neoplasm that affects the testis. "The rs995030 SNP of the KITLG gene, which has been highly and consistently associated with risk of testicular cancer and is in strong linkage disequilibrium (r2>0.8) with other susceptibility SNPs was selected for the present analyses." (PMID 28036409, 2016). "The KITLG somatic mutations are in a linkage disequilibrium block with rs995030, a marker SNP rs995030 which is strongly associated with testicular cancer risk." (PMID 23091610, 2012). "Applying the method to testicular cancer, we found a nominally significant M×M interaction between single nucleotide polymorphisms from C-Kit Ligand (KITLG) and Sex Hormone Binding Globulin (SHBG) using 210 families (relative risk 2.2, P = 0.03)." (PMID 22740241, 2012). "Association between the KITLG SNP rs995030 and testicular cancer." (PMID 28036409, 2016). "We studied both subfertility and the strongest known testicular cancer susceptibility gene, the c-KIT ligand (KITLG), whose pathway is involved in spermatogenesis." (PMID 28036409, 2016). "SPRY4 inhibits the mitogen-activated protein kinase pathway (MAPK) which is activated by the KITLG-KIT pathway, which has been associated with testicular cancer." (PMID 23091610, 2012). "Likewise, mutations in the KITLG locus were mostly closely linked to an increased risk of testicular cancer and were not connected to any other TDS symptoms." (PMID 23519268, 2013).
glioblastoma (6 papers, 2010 to 2025). The most malignant astrocytic tumor (WHO grade IV). "KITLG is an upregulated DEG and is reported to mediate innate resistance to the chemotherapeutics displayed by glioblastoma cells." (PMID 40032892, 2025). "Genes that show higher expression in astrocytoma compared to glioblastoma were CX3CL1, CSF1 (MCSF), CCL3 (MIP1α), CCL4 (MIP1β), TGFα, FLT3LG, CXCL5, CCL19 while KITLG (SCF) and NGF were equally expressed in the two tumor types." (PMID 35301393, 2022).
neuroblastoma (6 papers, 2012 to 2022). Neuroblastoma (NB) is the most common solid, extracranial childhood tumor. "Cytokines selected from primary, secondary, and tertiary clusters with respect to EPO (IL-11, KITLG, LIF, THPO) were chosen as experimental candidates, to test their effect on Egr2 mRNA expression in serum-starved EPOR-B104 neuroblastoma cells exactly." (PMID 24672526, 2014).
Waardenburg syndrome type 2 (5 papers, 2020 to 2023). Waardenburg syndrome type 2 (WS2) is an autosomal dominant subtype of Waardenburg syndrome (WS), characterized by varying degrees of deafness and pigmentation anomalies of eyes, hair and skin, but without dystopia canthorum. "Some pigmentation disorders in humans are thought to be caused by KITLG mutations, such as Waardenburg syndrome type 2, as well as familial progressive hyper- and hypopigmentation." (PMID 36140679, 2022). "Coding sequence variants in KITLG have been shown to cause familial progressive hyperpigmentation with or without hypopigmentation as well as Waardenburg syndrome type 2 (with pigmentary abnormalities)." (PMID 31936656, 2020). "Waardenburg syndrome type 2 was discussed as a cause for S13, but as none of the clinical features are known in the patient and the KITLG variant is of uncertain significance (VUS), a genetic cause could not be established." (PMID 36675424, 2023).
multiple myeloma (4 papers, 2013 to 2025). "In multiple myeloma cells, DAZAP1 promoted cell proliferation by enhancing the alternative splicing of KITLG mRNA, activating the ERK signaling pathway." (PMID 40401521, 2025).
nevus (4 papers, 2011 to 2026). Nevus (or naevus, plural nevi or naevi, from nævus, Latin for "birthmark") is the medical term for sharply circumscribed[1] and chronic lesions of the skin or mucosa. "The analysis confirmed previously established nevus-associated loci (MTAP, PLA2G6, IRF4) and uncovered novel associations with single-nucleotide polymorphisms (SNPs) in KITLG and a region on chromosome 9q32." (PMID 41596618, 2026).
ovarian tumor (4 papers, 2013 to 2022). "Given that ovarian tumors express high levels of stem cell factor (KIT ligand), inhibition of the c-KIT/PI3K/Akt/mTOR pathway may reduce IDO expression, and may also limit signaling through CREB, STAT3 and HIF-1α, all of which potentially contribute to immune suppression and disease progression." (PMID 26343197, 2015). "KITLG helps c-Kit+ cancer stem cell (CSC) survival in selective culture conditions and promotes their canonical stemness properties, interestingly only the expression of membrane-bound SCF can be detected in ovarian tumor cells." (PMID 36242590, 2022).
seminoma (4 papers, 2019 to 2026). A radiosensitive malignant germ cell tumor found in the testis (especially undescended), and extragonadal sites (anterior mediastinum and pineal gland). "In the context of the cKIT-KITLG loop, either autocrine or paracrine, the loss of KITLG in non-seminomas is of interest." (PMID 31658757, 2019). "For example the KITLG-IGFR/EGFR-Grb2-Sos-Raf-Ras-ERK path is specific to seminomas." (PMID 33251139, 2020).
uveal melanoma (4 papers, 2013 to 2024). A melanoma derived from melanocytes of the uveal tract. "Specifically, in uveal melanoma, KITLG-dependent stimulation facilitates the proliferation and transformation of uveal melanoma cells via SCF/c-KIT autocrine loop activation." (PMID 38213737, 2024).
bipolar disorder (3 papers, 2018 to 2025). A disorder of the brain that causes unusual shifts in mood, energy, activity levels and the ability to carry out day-to-day tasks. "Here, we follow up the previously reported association of KITLG methylation with childhood adversity and stress reactivity by exploring the relationship between KITLG DNA methylation levels at the locus cg27512205 and bipolar disorder." (PMID 30723428, 2018). "Since impaired cortisol stress reactivity is associated with bipolar disorder, this could imply an association between KITLG methylation with bipolar disorder." (PMID 30723428, 2018). "It is this finding that led to the expectation of KITLG hypermethylation among bipolar disorder patients exposed to higher levels of childhood adversity." (PMID 30723428, 2018). "In conclusion, this study shows that KITLG methylation level is significantly lower in bipolar disorder despite relatively high childhood adversity exposure in bipolar disorder patients." (PMID 30723428, 2018). "In contrast to the positive association between childhood adversity with KITLG methylation in controls, we did not observe such an association in bipolar disorder patients." (PMID 30723428, 2018). "Considering to the low frequency of the comorbid psychiatric diagnosis in the bipolar disorder group, we do not specifically exam the association of each comorbid psychiatric diagnosis with KITLG methylation level." (PMID 30723428, 2018). "A putative link between KITLG function and bipolar disorder is that the ligand of the C-kit receptor (SCF), is involved in hematopoiesis, neurogenesis, and neuroprotection and induces glucocorticoid receptor gene (NR3C1) expression in response to stress induced erythropoiesis." (PMID 30723428, 2018). "However, visual inspection of the relations between childhood adversity and KITLG methylation points to systematic lower KITLG methylation in bipolar disorder." (PMID 30723428, 2018). "To examine this hypothesis, we investigate the relationship between KITLG (cg27512205) methylation level in a case-control sample of bipolar disorder patients and healthy controls and the relation to childhood adversity." (PMID 30723428, 2018). "Moreover, bipolar disorder patients also report higher levels of childhood adversity, which may lead to higher KITLG methylation if the previous findings in healthy controls were to be extrapolated to bipolar disorder patients." (PMID 30723428, 2018). "Therefore, the current study hypothesizes the presence of higher KITLG methylation in bipolar disorder patients as compared to healthy controls in agreement with expected higher level of childhood adversity." (PMID 30723428, 2018). "This implies a positive regulation of KITLG gene to NR3C1 expression, a key gene in the stress response, that in term plays a role in bipolar disorder and the response to trauma." (PMID 30723428, 2018). "Although unexpected, these findings are consistent with other recent reports that the protein coded by KITLG gene, known as stem cell factor (SCF), is significantly higher in children of bipolar disorder patients who develop mood disorder later in life." (PMID 30723428, 2018).
chronic lymphocytic leukemia (3 papers, 2016 to 2022). "Recent findings of KITLG in chronic lymphocytic leukemia (CLL) indicate that KITLG is overexpressed in CLL B cells compared to healthy B cells, and the membrane-bound isoform plays a leading role." (PMID 36242590, 2022).
colorectal adenocarcinoma (3 papers, 2014 to 2021). The most common type of colorectal carcinoma. "There are 59 invasive colorectal adenocarcinoma cases available in the database; among them, 1 case (TCGA-AA-3680) shows homozygous deletion of miR-34c and 3 cases (TCGA-AA-3561, TCGA-AG-3586 and TCGA-AG-3892) exhibit KIT mRNA up-regulation but none cases show decreased miR-34a or KITLG alteration." (PMID 25213795, 2014).
male infertility (3 papers, 2015 to 2021). The inability of the male to effect fertilization of an ovum after a specified period of unprotected intercourse. "In humans, KITLG has been associated with male infertility and oocyte growth and follicular development." (PMID 33436104, 2021). "In human, a significant association for male infertility could be detected in KITLG affecting sperm count in patients." (PMID 26452642, 2015).
sarcoma (3 papers, 2013 to 2016). A usually aggressive malignant neoplasm of the soft tissue or bone. "Since mutated KIT receptor is known to drive GIST sarcomas, it seemed possible that the moderate amplification of KITLG and resulting overexpression of the c-KIT ligand could be a driver, providing an autocrine loop." (PMID 27409346, 2016).